HDAC3 (histone deacetylase 3)
Diseases named in the same sentence as HDAC3 in open-access papers (continued):
Sharing a sentence is not in itself a finding about the gene and the disease.
colon carcinoma (42 papers, 2011 to 2024). "Based on evidence that HDAC inhibition activates p16, we confirmed HDAC3 interactions on p16 to be higher in colon tumors of WT vs. Nrf2−/+ mice, and inversely associated with p16 mRNA levels." (PMID 26388957, 2015). "Previous studies demonstrated that inhibition of HDAC2 and HDAC3 increased p21 expression in human colon cancer." (PMID 39273544, 2024). "Previous studies have reported that HDAC3 is overexpressed in various cancers, such as breast, prostate, and colon cancers." (PMID 38805168, 2024). "To assess the effect of HDAC3 inhibition on colon cancer, we examined cell proliferation and apoptosis after inhibiting HDAC3 in HCT116 cells." (PMID 38805168, 2024). "TIP60 plays a crucial role in the regulation of HDAC3 transcription, thereby influencing cell proliferation and apoptosis in colon cancer." (PMID 38805168, 2024). "Based on these results, we proposed that TIP60 regulates the expression of HDAC3 in colon cancer cells." (PMID 38805168, 2024). "At the same time, the downregulation of pyruvate helps colon cancer cells to avoid cell death due to HDAC1/HDAC3 inhibition." (PMID 36839472, 2023). "In particular, SFN-treated tissue lysates from colon tumors displayed decreased HDAC3 levels and CDKN2a/p16 mRNA expression and enhanced global histone H4 acetylation." (PMID 36765652, 2023). "Gene silencing of HDAC3 in human colon cancer results in cell growth inhibition, differentiation, and increased apoptosis." (PMID 34973135, 2023). "HDAC3 has been shown to regulate the biological activities of colon cancer cells, including proliferation, differentiation and apoptosis." (PMID 37553641, 2023). "While inhibiting the metastasis of colon cancer by recruiting histone deacetylase 3 (HDAC3) to the Runx2 promoter, CBX4 promotes the metastasis of osteosarcoma by recruiting GCN5, which catalyzes H3K27 acetylation of the Runx2 promoter." (PMID 37691307, 2023). "In colon cancer, HDAC3 knockdown can suppress β-catenin translocation from the plasma membrane to the nucleus and increase the expression of Wnt inhibitors TLE1, TLE4 and SMO." (PMID 34991620, 2022). "In colon cancer cells, silencing of HDAC3 expression by RNA interference (RNAi) resulted in growth suppression, accompanied by increased expression of p21 and apoptosis." (PMID 35646715, 2022). "The expression of HNF4α is controlled by epigenetic mechanisms and siRNA-mediated silencing of HDAC3 and 4 reduces its expression as well as target gene transcription in colon carcinoma cells." (PMID 32982982, 2020). "In colorectal cancer, lncRNA SBF2-AS1 promotes colon cancer cell growth and invasion via suppressing miR-619-5p activity and facilitating Histone Deacetylase 3 (HDAC3) expression." (PMID 32976115, 2020). "HDAC3 knockdown impaired DNA repair and resulted in growth inhibition of human colon cancer cell lines." (PMID 33298132, 2020). "It has also been shown that cotransfection of KLF4 with HDAC3 synergistically represses cycling B1 transcription in human colon cancer cells." (PMID 30936247, 2019). "To further confirm that our model indeed mimics the human disease we also determined the change in expression of four more proteins namely UCH-L1, P-21, HDAC-3, and A33 which play a crucial role in the development of colon cancer." (PMID 31766149, 2019). "Several studies have demonstrated increased expression of the class-I HDACs: HDAC1, HDAC2, and HDAC3, in multiple human cancers, including colon cancer." (PMID 29152115, 2017). "The up-regulation of HDAC3 protein expression has been reported in human colon tumours and knocking down of HDAC3 expression by RNA interference in colon cancer cell lines resulted in growth inhibition, a decrease in cell survival and increased apoptosis." (PMID 26560874, 2016). "As in the ApcMin/+ mouse, SFN suppressed tumorigenesis in the DMH model, and this was accompanied by reduced HDAC activity and HDAC3 protein expression in the colon tumors." (PMID 26388957, 2015).
colon carcinoma (continued). "The corroboration of HDAC3 as a target of SFN in vivo is important considering the critical role of this HDAC in regulating colon cancer growth and tumorigenesis." (PMID 26388957, 2015). "We reported that a natural compound, sulforaphane (SFN), targets HDAC3 for protein turnover in human colon cancer cells." (PMID 26388957, 2015). "Studies have reported the ability of sulforaphane to retard HDAC3 protein expression in human colon cancer cells." (PMID 28930206, 2015). "It is known that colon cancer cells over-express HDAC3, a protein required for enhanced genomic stability." (PMID 28930206, 2015). "From these findings it is expected that aberrant expression of HDAC3 and other class I HDACs play a role in the progression of colon cancer." (PMID 23914191, 2013). "HDAC1 and HDAC3 are overexpressed in colon cancer cells and in primary colon cancer, and siRNA (small interfering RNA) mediated silencing of HDAC1 and HDAC3 in colon cancer cells induced apoptosis." (PMID 22496748, 2012). "Over expression of HDAC3 has been seen in colon cancer cell lines, and strong expression of HDAC3 correlates with a poor prognosis in patients with adenocarcinoma of the lung." (PMID 21346816, 2011). "We recently reported SFN-induced loss of HDAC3 and HDAC6 protein expression in a time-dependent manner in HCT116 colon cancer cells, leading to acetylation of histone H4 and tubulin, respectively." (PMID 22247744, 2011). "In human colon cancer cells, silencing of HDAC3 resulted in growth inhibition, decreased cell survival, and increased apoptosis." (PMID 21624135, 2011). "The positivecorrelation between EGFR and HDAC3 expression was also observed in fourteenpairs of human colon tumor and adjacent normal tissues." (PMID 21464950, 2011). "Furthermore, through GO analysis, we observed increased expression levels of HDAC3 in various cancers and verified that HDAC3 influences cell development and malignancies in colon cancer." (PMID 38805168, 2024). "Therefore, our findings suggest that TIP60 acts as a tumor suppressor by regulating HDAC3 transcription in colon cancer cells." (PMID 38805168, 2024). "To further investigate whether TIP60 regulates colon cancer progression via HDAC3, we examined its role in modulating HDAC3 target genes." (PMID 38805168, 2024). "We investigated whether TIP60 could regulate the expression of HDAC3 and suppress colon cancer cell proliferation." (PMID 38805168, 2024). "The fact that DNMT3A and HDAC3 are degraded in methylation-sensitive colon cancer cells in part via blocking their connection with the E3 ubiquitin ligase UHRF1 could explain this decrease in expression." (PMID 35327559, 2022). "Second-generation BET degrader plus HDAC3-specific inhibition (dBET6 + BG45) was highly effective in metastasis-lineage colon cancer cells, exhibiting marked downregulation of ERCC2 in monolayers, spheroids, and xenografts, coinciding with antitumor outcomes in vivo." (PMID 33809839, 2021). "Second, ERCC2 was the most highly downregulated RNA transcript in human colon cancer cells, plus Ercc2 in rat tumors, after treatment with the histone deacetylase 3 (HDAC3) inhibitor sulforaphane (SFN) plus JQ1, which is an inhibitor of the bromodomain and extraterminal domain (BET) family." (PMID 33809839, 2021). "Studies have shown roles of HDAC3 or HDAC8 in colon cancer cells." (PMID 31083396, 2019). "HDAC3 expression is increased in human tumour samples of colon cancer compared with normal tissue." (PMID 26560874, 2016). "We specifically sought to test the hypothesis that Nrf2 status might affect HDAC3 protein expression levels in colon tumors, and thus the inhibitory response to SFN acting preferentially on HDAC3." (PMID 26388957, 2015). "Gliomas and colon cancer cells have both been shown to have elevated levels of HDAC3." (PMID 26450925, 2015). "HDAC3 knockdown in human colon cancer cells recapitulated the effects of SFN on p16 induction." (PMID 26388957, 2015).
colon carcinoma (continued). "Indeed, both sodium butyrate and stable knockdown of HDAC3 in colon cancer cells leads to reduction in Myc levels by stimulating membrane localization of β-catenin, a Wnt pathway effector whose nuclear localization is necessary for Myc expression." (PMID 22582024, 2011). "In addition, HDAC3 reduces p21 activity and apoptosis in colon cancer." (PMID 38805168, 2024). "Consequently, TIP60 may function as a tumor suppressor by inhibiting HDAC3 expression in colon cancer cells." (PMID 38805168, 2024). "In addition, high levels of HDAC3 expression have been reported in colon cancer." (PMID 35646715, 2022). "The expression of histone deacetylase 3 (HDAC3) is upregulated, whereas the expression of tat interactive protein, 60 kDa (TIP60) is downregulated in colon cancer." (PMID 38805168, 2024). "TGIF2 has been reported to interact with PKM2 and recruit HDAC3 to the E-cadherin promoter, promoting EMT in colon cancer." (PMID 36647029, 2023). "In colon cancer, TGIF2 was reported to interact with PKM2 to recruit HDAC3 to the E-cadherin promoter, leading to EMT upon EGF stimulation." (PMID 31871777, 2019). "In colon cancer cells, TGIF2 directly interacts with PKM2 in the nucleus by EMT stimulation, and recruits histone deacetylase 3 to the CDH1 (E-cadherin) promoter sequence, which subsequently deacetylates histone H3 and suppresses CDH1 transcription." (PMID 30333907, 2018). "Specifically, in human colon carcinoma cells, the authors showed that deacetylation of SP1 by HDAC3 results in increased binding of SP1 to the EGFR promoter." (PMID 26243279, 2015). "In colon tumors, daily SFN lowered HDAC activity and HDAC3 protein expression while increasing global histone H4 acetylation." (PMID 26388957, 2015). "Compounds T247 and T326 also induced a dose-dependent selective increase of NF-κB acetylation in human colon cancer HCT116 cells, indicating selective inhibition of HDAC3 in the cells." (PMID 23874714, 2013). "Ectopic express HDAC3 induceda greater magnitude of EGFR mRNA and a positive correlation between EGFR and HDAC3expression in colon cancer patients." (PMID 21464950, 2011). "Because we found that the transcription of HDAC3 was repressed by TIP60 and that HDAC3 had oncogenic activities in colon cancer, we tested whether TIP60-mediated suppression of HDAC3 affected the proliferation or apoptosis of HCT116 cells." (PMID 38805168, 2024). "A study revealed that SFN treatment caused G2/M arrests during which normal control cells showed increased HDAC3 activity but not in SFN-treated colon cancer cells." (PMID 36765652, 2023). "Exogenous overexpression of AKAP12 in Lovo colon cancer cell line inhibits tumor cell proliferation, migration, and invasion ability; in contrast, AKAP12 silencing or AKAP12/HDAC3 cosilencing promotes tumor cell proliferation, colony-forming ability, and cell cycle progression." (PMID 36148016, 2022). "One of the proposed mechanisms identified in colon cancer cells suggest that the catechin may contribute to the degradation of both DNMT1 and HDAC3." (PMID 32429384, 2020). "HDAC3 activity may be dependent on the activity of class IIa HDAC4 protein, as Sp1-dependent targeting of HDAC4 to the proximal p21 promoter in colon cancer cells was shown." (PMID 23914191, 2013). "Additionally, protein expression of HDAC3 was significantly up-regulated in a panel of human colon tumors compared with adjacent normal mucosa and in small intestinal adenomas derived from APC mutant mice epithelia, establishing a link between HDAC3 expression and intestinal cell transformation." (PMID 23914191, 2013). "However, the relationship between HDAC3 and TIP60 in colon cancer has not been clearly elucidated." (PMID 38805168, 2024).
diabetes (40 papers, 2013 to 2026). "HDAC3 inhibition demonstrated superior benefits in mitigating diabetes-associated cardiovascular damage." (PMID 40660005, 2025). "HDAC3 being both associated with the termination of EndMT while being upregulated in diabetes is an interesting avenue of future studies." (PMID 36777351, 2023). "We assessed the impact of HDAC3 depletion in macrophages on the development of AS in these diabetes-prone, AS-susceptible mice." (PMID 37215106, 2023). "Collectively, these findings suggest that macrophage-specific HDAC3 depletion significantly ameliorates AS severity in diabetes-prone, AS-susceptible mice." (PMID 37215106, 2023). "BHB treatment can inhibit HDAC3 to promote claudin-5 generation and antagonize diabetes-associated cardiac microvascular hyperpermeability." (PMID 35409148, 2022). "The mechanisms of how HDAC3 regulates type 1 and type 2 diabetes mellitus-induced hepatic injury are different, although HDAC3 has been implicated in both diseases." (PMID 34301918, 2021). "Future studies should investigate the potential of HDAC3 as an epigenetic regulator in diabetes-associated vasculopathy." (PMID 33736642, 2021). "One Chinese case-control study also demonstrated that the single nucleotide polymorphism of HDAC3 including rs11741808, rs2547547, and rs2547547 polymorphism was related to type 2 diabetes mellitus." (PMID 34301918, 2021). "These clinical studies suggested that the genetic change of HDAC3 is closely associated with the development of diabetes mellitus and cerebrovascular disease." (PMID 34301918, 2021). "A substantial increase in histone deacetylase 3 (HDAC3) expression is implicated in the pathological process of diabetes and stroke." (PMID 30906786, 2019). "Epigenetically altered macrophages promote development of diabetes-associated AS, which could be prevented through HDAC3 depletion." (PMID 37215106, 2023). "Interestingly, tissue-specific deletion of HDAC3 has been associated with chronic inflammatory disease models for diabetes, heart disease, Alzheimer’s disease, and IBD." (PMID 36602872, 2023). "Finally, the inhibition of HDAC3 reduces ROS production, endothelial impairment and alleviates endothelial injury caused by type 2 diabetes mellitus (T2DM)." (PMID 37072432, 2023). "Augmentation of HDAC3 leads to diabetes, and the present study showed its association with DFU." (PMID 33096729, 2020). "HDAC3 inhibition rescued diabetes-induced junction proteins loss, which might contribute to the protective effect of HDAC3 inhibition on diabetic state-induced BBB permeability." (PMID 31101061, 2019). "However, there are many questions remain to be further elucidated, especially regarding the role and the underlying mechanisms of HDAC3 in the pathophysiology of diabetes complicated with ischemic stroke." (PMID 30906786, 2019). "Numerous enzymes associated with H3K9me3, the mark associated with heterochromatin, including acetyltransferases (SRC‐1/Ncoa1), deacetylases (Hdac3), methyltransferases (Suv39 h1 and G9a/Ehmt2), and demethylases (Jhmdh2a/Kdm3a, Jmjd2c/Kdm4c), have been linked to fatty liver, diabetes, and obesity." (PMID 29484800, 2018). "Interestingly, three single nucleotide variants of the HDAC3 gene were shown associated with type 2 diabetes mellitus in a Chinese population." (PMID 27904654, 2016). "Moreover, the findings in this study could be strengthened by examining the potential therapeutic effects of pharmacological inhibition or modulation of HDAC3 activity in preclinical models of diabetes-associated atherosclerosis." (PMID 37215106, 2023). "In contrast, variants of HDAC3 contribute to an increased prevalence of type 2 diabetes mellitus (DM) in the Chinese Han population." (PMID 25322459, 2014). "Inhibiting HDAC3 mediated Nrf2 activation in alleviating diabetes‐induced liver injury in mice showed promising results." (PMID 39143689, 2025).
diabetes (continued). "Recent evidence suggests a positive correlation between increased HDAC3 activity in peripheral blood mononuclear cells and inflammatory markers in type 2 diabetes mellitus patients." (PMID 39143689, 2025). "Fibroblast growth factor 21 (FGF21), a regulator of lipid and glucose metabolism, protects against diabetes-induced cardiovascular injuries but is inhibited by HDAC3." (PMID 40660005, 2025). "The role of HDAC3 inhibitors in the treatment of diabetes has been widely recognized, and selective HDAC3 inhibitors can become potential antidiabetic drugs." (PMID 38405061, 2024). "In vivo studies revealed that Hdac3 knockdown or Mbnl1 overexpression alleviated diabetes symptoms through circMlxipl-regulated ChREBP in diabetic mice." (PMID 39580381, 2024). "The therapeutic potential of HDAC3 inhibitors in managing diabetes is widely acknowledged, and high selective HDAC3 inhibitors have the ability to develop into promising antidiabetic medications." (PMID 38405061, 2024). "Collectively, these findings indicate that Hdac3 knockdown or Mbnl1 overexpression alleviated diabetes symptoms, possibly through circMlxipl-regulated ChREBP in vivo." (PMID 39580381, 2024). "Mechanistic studies have reported that inhibition of Hdac3 is implicated in the regulation of gluconeogenesis, oxidative metabolism and hepatic FGF21 expression in diabetes." (PMID 39580381, 2024). "Though no mechanistic link has been made between histone modifications and EndMT in the context of diabetes, HDAC3 has been found to be significantly increased in T2DM patients and HDAC3 mRNA levels were positively correlated to poor glycemic control." (PMID 36777351, 2023). "In the hearts of rats with streptozotocin (STZ)-induced diabetes, HDAC3 enzymatic activity led to ischemic cardiac damage." (PMID 37674539, 2023). "HDAC3 inhibited apoptosis in peripheral blood mononuclear cells by downregulating miR-296-5p and upregulating Bcl-xl, thereby aggravating type 1 diabetes mellitus." (PMID 34301918, 2021). "In mice with type 2 diabetes mellitus, intestinal epithelial cell-specific disruption of Hdac3 prevented obesity and dysregulation of glucose metabolism." (PMID 34301918, 2021). "Conversely, HDAC3 was found to be downregulated in the pancreas of children with type 1 diabetes mellitus." (PMID 34301918, 2021). "Inhibition of HDAC3 in diabetic mice ameliorates diabetes-induced liver damage, and reduces oxidative stress and aortic injury by activating Nrf2 signaling." (PMID 33736642, 2021). "The protective effect of HDAC3 inhibition in diabetes can be partly attributed to reduced eNOS uncoupling and activation of Nrf2 signaling through the modulation of Nox4–Nrf2 redox imbalance." (PMID 33736642, 2021). "We also explored the HDAC3 protein level in the liver because of its reported correlation with diabetes." (PMID 33662521, 2021). "HDAC3 inhibition relieved endothelial injury and dysfunction induced by type 2 diabetes mellitus by blocking the interaction of Keap1 and Nrf2 in a Nox4-dependent manner." (PMID 34301918, 2021). "PD106 and BRD3308 are also selective HDAC3 inhibitors used for the treatment of Friedreich’s ataxia, diabetes mellitus, and HIV infection." (PMID 34301918, 2021). "Here, we observed that the clock genes Rev-erbα, BMAL1, and C/EBPβ oscillations were altered in the hearts of rats with streptozotocin (STZ)-induced diabetes, with upregulated HDAC3 expression." (PMID 33414413, 2021). "Concordantly, the downregulation of Hdac3 has been considered as a strategy for developing new ways for the treatment of diabetes." (PMID 33240312, 2020). "Results from the gene expression dataset have revealed that Hdac3 is negatively correlated with miR-296-5p and can inhibit the occurrence of diabetes." (PMID 33240312, 2020). "Suppression of HDAC3 enhances oxidative metabolism, regulates gluconeogenesis, reduces hyperglycaemia, and increases insulin secretion, which are conductive in improving diabetes." (PMID 30906786, 2019).